ACSL5 (acyl-CoA synthetase long chain family member 5)
Diseases named in the same sentence as ACSL5 in open-access papers (continued):
Sharing a sentence is not in itself a finding about the gene and the disease.
melanoma (3 papers, 2022 to 2024). A malignant, usually aggressive tumor composed of atypical, neoplastic melanocytes. "Upregulation of additional genes from the bile acid and peroxisome signaling pathways was also evident in TIL gene and pathway expression analysis, including upregulation of SOD1, ACSL5, FADS2, CAT, DHCR24, SLC27A2, and IDH2 in melanoma TILs compared to pCD8s." (PMID 38023136, 2023). "Based on the FAM molecular subtypes, we identified the 6 FAMGs (ACSL5, ALOX5AP, CD1D, CD74, IL4I1, TBXAS1) that play vital regulatory roles in the melanoma TME." (PMID 36466837, 2022).
non-alcoholic steatohepatitis (3 papers, 2017 to 2023). "SIRT6 protein levels are decreased and ACSL5 K361 acetylation levels are increased in the liver of nonalcoholic steatohepatitis (NASH) patients compared to those in healthy controls." (PMID 36831330, 2023). "However, in a transgenic murine PTEN knockout, non-alcoholic steatohepatitis (NASH)-induced model for HCC, a quantitative proteomic study found that ACSL1 protein levels were fractionally decreased and ACSL5 levels reciprocally up-regulated." (PMID 32286604, 2020).
ovarian carcinoma (3 papers, 2016 to 2022). A malignant neoplasm originating from the surface ovarian epithelium. "The better prognosis in breast, lung and ovarian cancer patient with higher ACSL5 expression was in accordance with the result from Oncomine and PrognoScan database, implying the tumor suppressor role of ACSL5 in breast, lung and ovarian cancer." (PMID 27171439, 2016). "The analysis indicated that the brain cancer patient with higher ACSL5 expression had poor survival; in contrast, the patient with higher ACSL5 expression had good survival in breast, colorectal, lung and ovarian cancer." (PMID 27171439, 2016). "A significant decrease of ACSL5 was observed in breast, liver, lung, and ovarian cancer." (PMID 27171439, 2016).
steatosis (3 papers, 2016 to 2023). Increased lipid within the cytoplasm of cells. "Up-regulation of ACSL5 is associated with the hepatocyte steatosis and is sensitive to fatty acid-induced hepatic cell death." (PMID 27171439, 2016). "In mice and patients with simple steatosis that exhibit slightly lower levels of SIRT6, most ACSL5 proteins are deacetylated by cytoplasmic SIRT6." (PMID 36880305, 2023).
endometrial carcinoma (2 papers, 2017 to 2024). A malignant tumor arising from the epithelium that lines the cavity of the uterine body. "Moreover, the data from The Human Protein Atlas indicate that ACSL1, ACSL4, and ACSL5 are favorable prognostic markers in renal cancer, urothelial cancer, and endometrial cancer." (PMID 38539505, 2024).
liver cancer (2 papers, 2016 to 2024). An epithelial or non-epithelial malignant neoplasm that arises from the liver. "The hub gene in our analysis ACSL5, ALDOA, and HKDC1 are directly associated with liver cancer." (PMID 38648205, 2024). "ACSL5 promotes the fatty acid uptake which results in fat storage or β-oxidation in liver cancer." (PMID 27171439, 2016).
lupus (2 papers, 2011 to 2019). "Several in vivo and in vitro studies have indicated that ACSL5 may play an important role in the immune dysfunction of lupus-like mouse models." (PMID 31159150, 2019).
prostate carcinoma (2 papers, 2016 to 2020). A carcinoma that arises from epithelial cells of the prostate gland. "Our analysis revealed that ACSL5 is significantly overexpressed in bladder, esophageal, lung, pancreatic and prostate cancer." (PMID 27171439, 2016).
type 2 diabetes (2 papers, 2018 to 2019). "Also, ACSL5 rs7903146 is one of the most strongly associated type 2 diabetes loci and resides within a regulatory region of an ACSL5 promoter." (PMID 31053784, 2019). "On the other hand, the role of ACSL5 in the context of type 2 diabetes pathogenesis still needs to be fully elucidated, including how it relates to PARP-1, before one can meaningfully embark on a similar study for that particular factor." (PMID 29392078, 2018).
astroglioma (1 paper, 2019). "Specific ACSL5-isoform transfection in HEK239T (kidney), U87 (astroglioma), and HOG (oligodendrocyte) cells showed the Spl protein to be the causal factor of cell-growth inhibition, despite its reduced protein expression." (PMID 31053784, 2019).
cerebrovascular diseases (1 paper, 2025). "The ACSL family consists of five isoforms—ACSL1, ACSL3, ACSL4, ACSL5, and ACSL6—each of which has been implicated in the pathogenesis, treatment, and prognosis of diverse conditions, including metabolic disorders, cancers, cardiovascular and cerebrovascular diseases, and other clinical conditions." (PMID 41288931, 2025).
colon adenocarcinoma (1 paper, 2015). "Previous reports have indicated that other ACS isozymes, such as ACSL4 and ACSL5, are overexpressed in various types of cancer, including colon adenocarcinoma." (PMID 25749516, 2015).
COVID-19 (1 paper, 2024). A disease caused by infection with severe acute respiratory syndrome coronavirus 2. "In addition, both ACSL5 and HSD17B4 were found to be associated with fatty acid synthesis, which may indicate the impact of COVID-19 and ICC on lipid metabolism." (PMID 38648205, 2024).
diabetes (1 paper, 2020). "The C/C cells showed differential binding affinity compared to C/T cells in some previously identified TCF7L2 target genes that are involved in diabetes, such as ACSL5, ATM, AKT2, LEF1, and PDK4." (PMID 32651957, 2020).
endometriosis (1 paper, 2025). The growth of functional endometrial tissue in anatomic sites outside the uterine body. "There has been limited research on the roles of ACSL5, PLA2G4A, EHHADH, GPAM, PLA2G15, SULT2A1, and ACSL3 in endometriosis, highlighting the necessity for further investigation to elucidate their contributions to its pathogenesis." (PMID 40527850, 2025).
enteritis (1 paper, 2023). Inflammation of the small intestine. "The expression of some of these genes was also found to be altered when Atlantic salmon were fed on a diet with a high FM replacement with plant proteins sources, and particularly during soybean-meal-induced enteritis (e.g., acyl-CoA synthetase long-chain family member 5 and 6 downregulation)." (PMID 37508368, 2023).
Failure to thrive (1 paper, 2023). Failure to thrive (FTT) refers to a child whose physical growth is substantially below the norm. "During the neonatal period, Acsl5 variant is associated with recurrent vomiting, diarrhea, and failure to thrive." (PMID 36817150, 2023).
hypertriglyceridemia (1 paper, 2021). A laboratory test result indicating elevated triglyceride concentration in the blood. "PD strain displays significant downregulation of three acyl-CoA-generating enzymes (ACSM3, ACSM2A, ACSL5), which can contribute to the lower ability to utilize fatty acids and hypertriglyceridemia in this strain." (PMID 33923085, 2021).
hypothyroidism (1 paper, 2021). Abnormally low levels of thyroid hormone. "In our study, the expression of Fasn, Acsl1, Acsl5, Ehhadh, and Acox1 were significantly down-regulated in hypothyroidism rats, indicating that the synthesis of fatty acid and the oxidation process of fatty acids were inhibited." (PMID 33959028, 2021). "These DEPs including Pygl, Pklr, Pc, Ehhadh, Acox1, Fasn, Acly, Acsl1, Acsl5, Pgm1, Suclg1, Gpt, Idh1, Fh, and Adh1 maight be as target proteins of AMR and its fractions for hypothyroidism." (PMID 33959028, 2021).
inflammatory bowel disease (1 paper, 2020). A spectrum of small and large bowel inflammatory diseases of unknown etiology. "Previous reports associated patients with inflammatory bowel disease (IBD) with the over-expression of ACSL1 and ACSL5 in the terminal ileum and colon." (PMID 33050166, 2020).
kidney transplant (1 paper, 2025). A surgical procedure in which one or both kidneys from a donor are implanted into a recipient. "Having shown that ACSL5 expression is associated with kidney transplant rejection, we tried to find out if there was a corresponding urinary metabolomic signature." (PMID 40546938, 2025). "We show that ACSL5 is a constituent of a gamma interferon-related gene signature linked to rejection in kidney transplant recipients and the urinary metabolome of kidney transplant recipients who experienced rejection exhibited a deficiency in ACSL5 substrates." (PMID 40546938, 2025).
lung diseases (1 paper, 2023). "Potential roles of target gene ACSL5 in lysoPC regulation were uncovered by comprehensively evaluating transcriptomic changes of ACSL5‐down‐regulated epithelial and ACSL5 expression among single‐cell subtypes of lung epithelia among different lung diseases." (PMID 36639836, 2023).
myeloma (1 paper, 2025). "ACSL1, ACSL3, ACSL4, and ACSL5 are expressed in primary myeloma cells and supportive of myeloma cell fitness, suggesting that broad targeting of the ACSLs could be impactful for MM patients." (PMID 39853696, 2025).
osteoporosis (1 paper, 2020). A condition of reduced bone mass, with decreased cortical thickness and a decrease in the number and size of the trabeculae of cancellous bone (but normal chemical composition), resulting in increased fracture incidence. "Several hub genes, including JUN and ACSL5, were found and may represent potential biomarkers or clinical targets for osteoporosis." (PMID 33329745, 2020).
periodontitis (1 paper, 2024). An acute or chronic inflammatory process that affects the tissues that surround and support the teeth. "ACSL5, NLRP12, CCRL2, and CEACAM3 were identified as hub genes and diagnostic genes in both PCOS and periodontitis." (PMID 38167332, 2024). "Through RF of the identified hub genes (ACSL5, NLRP12, CCRL2, and CEACAM3), pathways that activate the immune system were implicated in PCOS and periodontitis." (PMID 38167332, 2024). "The 4 hub genes ACSL5, NLRP12, CCRL2, and CEACAM3 may be diagnostic genes for PCOS and periodontitis." (PMID 38167332, 2024). "Additionally, the AUCs of ACSL5, NLRP12, CCRL2, and CEACAM3 in the periodontitis training dataset were 0.771, 0.819, 0.708 and 0.785, respectively, which also suggested the diagnostic values of 4 hub genes on periodontitis were strong." (PMID 38167332, 2024). "Genes such as ACSL5, NLRP12, CCRL2, and CEACAM3 were identified as the molecular link between PCOS and periodontitis." (PMID 38167332, 2024). "Intersection of the candidate genes 1 and 2 yielded 4 hub genes (ACSL5, NLRP12, CCRL2, and CEACAM3) involved in both PCOS and periodontitis." (PMID 38167332, 2024).
skin cancer (1 paper, 2023). "Of the five MOBILE-hypothesized connector genes (BST2, CLIC2, FAM83D, ACSL5, and HIST2H2AA3) between IRF1 and PD-L1, BST2 was recently recognized as part of an immune/tumor-related signature that is significantly associated with the overall survival of skin cancer patients." (PMID 37414767, 2023).
thyroid cancer (1 paper, 2025). "We used LASSO Cox regression to construct a model for the evaluation of thyroid cancer prognosis, and a risk model consisting of six genes (ACSL5, HSD17B11, CCL5, NCF2, PSME1, and ACTB) was subsequently developed." (PMID 40299520, 2025). "Further validation using qRT–PCR in 100 paired thyroid cancer and adjacent normal tissues revealed consistent upregulation of ACSL5 and NCF2 in tumour tissues and downregulation of HSD17B11, CCL5, and ACTB." (PMID 40299520, 2025). "Therefore, targeting ACSL5 may enhance the therapeutic efficacy of ferroptosis inducers and improve the sensitivity of thyroid cancer to anticancer drugs." (PMID 40299520, 2025).
cancer (39 papers, 2009 to 2025). A tumor composed of atypical neoplastic, often pleomorphic cells that invade other tissues. "The ACSL5 gene encodes an enzyme involved in lipid metabolism, serving a critical function in the metabolic reprogramming of cancer cells." (PMID 40181462, 2025). "The splice variants in ACSL5 is associated with several types of cancer, and a deletion of ACSL5 can lead to intestinal lipid malabsorption." (PMID 36160020, 2022). "ACSL5 is implicated in several types of cancers and has a potential prognostic value." (PMID 31053784, 2019). "Genetic variants in ACSL5 may provide a linkage between the higher prevalence of cancer in obesity." (PMID 31053784, 2019). "Along with ACSL4 and ACSL1, ACSL5 has also been considered an immune-dependent cancer suppressor gene." (PMID 41288931, 2025). "Apart from being overexpressed in gliomas, ACSL5 demonstrates low expression in various other cancers, including colon and breast." (PMID 40932861, 2025). "ACSL5 is required for the de novo synthesis of lipids and fatty acid degradation, and its role in inflammation and cancer development has been reported." (PMID 35884586, 2022). "Higher levels of ACSL5 were seen in samples from patients with cancer in the right colon compared to the rectum when all samples were analyzed (AUC of 1)." (PMID 32452655, 2020). "The plasma levels of long‐chain‐fatty‐acid‐‐CoA ligase 5 (ACSL5, fold change of 6.3), an enzyme, were also higher in plasma samples from patients with cancer in the right colon." (PMID 32452655, 2020). "It is interesting to note that PTPRE is coexpressed with ACSL1 and ACSL5 in cancer, which warrants further investigation." (PMID 27171439, 2016). "ACSL5 mainly acts as a tumor suppressor in a variety of cancers, with an unclear role in RMS." (PMID 39927464, 2025). "Conversely, ACSL5 exhibits an opposing trend in cancer expression." (PMID 40932861, 2025). "Notably, in the present study, ACSL1, ACSL5, and NUDT19 seemed to be cancer-promoting genes, as their upregulation was associated with poor survival." (PMID 38406287, 2024). "In human cancer, ACSL5 shows pro- or anti-carcinogenic activity." (PMID 38539505, 2024). "ACSL5 was found to regulate cancer cell sensitivity in response to metabolites." (PMID 36639836, 2023). "ACSL5 isoenzymes play a dominant role in cardiolipin biosynthesis in mitochondria and may participate in cancer cell survival." (PMID 36733341, 2023). "ACSL5 has also been identified as the ferroptosis-related gene in cancer." (PMID 36507355, 2022). "In addition, ACSL5 also facilitates the transportation of exogenous fatty acids into cancer cells by cooperating with fatty acid transporters." (PMID 28786914, 2017). "To confirm the role of ACSL5 in cancer, we analyzed the prognostic value using PrognoScan." (PMID 27171439, 2016). "On the other hand, ACSL5 may exert its specific tumor suppressor role in different types of cancer through promoting ceramide or Wnt2B palmitoylation." (PMID 27171439, 2016). "ACSL5 is localized to the mitochondria, and it converts free long-chain fatty acids with 16–18 carbons, such as oleic acid, linoleic acid, and palmitic acid, to fatty acyl-coenzyme A. ACSL5 participates in pro-apoptotic sensing and acts as a tumor suppressor in cancers." (PMID 39872359, 2022). "Moreover, the observed gradual increase in ACSL5 expression as tissue changes from normal to AAH and ADC may support the notion that ACSL5 contributes to cancer progression." (PMID 34943992, 2021). "Moreover, it has been described that ACSL5 plays a dominant role in vitro in the biosynthesis of mitochondrial cardiolipin and could be involved in cancer cell survival." (PMID 24625834, 2014). "Among these, PEBP1/STK11 co-expression strongly negatively correlates in all cancer types with enzymes that increase the biosynthesis of fatty acids such as members of the ACSL family (ACSL1, ACSL3, ACSL4, ACSL5, and ACSL6)." (PMID 40806276, 2025).
cancer (continued). "ACSL5 and ALAS2 were downregulated in MCR group, they were all involved in fatty acid metabolism and played different roles in cancer." (PMID 37268653, 2023). "Based on function, the 12 FRGs can be grouped into four classes: Lipid metabolism (GPX4, LPCAT3, ACSL5, and ACSL6), antioxidant metabolism (CD44, SESN2, and AIFM2), iron metabolism (CISD1 and HSPB1), and cancer metabolism (SOCS1, FH, and G3BP1)." (PMID 34784264, 2022). "The 12 FRGs are divided into 4 categories according to their functions: lipid metabolism (GPX4, LPCAT3, ACSL5, ACSL6), antioxidant (CD44, SESN2, AIFM2), iron metabolism (CISD1, HSPB1), and cancer metabolism (SOCS1, FH, G3BP1)." (PMID 35559049, 2022). "Our study highlights the impact of ACOT8, ACSL5, FASN, HMGBCS2, and SCD1 genes in lipid metabolism along with their distinctive role in cancer initiation and progression." (PMID 32155177, 2020). "In addition to ACSL1, ACSL4, and ACSL5, ACSL3 and ACSL6 also contribute to cancer progression, with their roles to be further elaborated in the context of specific cancers." (PMID 41288931, 2025). "We found only 4 significant results in this analysis: First, low ACSL3 expression in Naïve B cells, and low ACSL5 and ACSL6 in Naïve CD8 cells, correlated with worse patient survival outcomes, demonstrating a potential reliance on these for an effective anti‐cancer immune response." (PMID 39853696, 2025). "ACSL5 mRNA expression up‐regulated in the basal, ciliated club, Goblet and mucous epithelia of ADC patients (vs. healthy), especially in ciliated, club and Goblet cells which differed from patients with COPD, IPF, SSC and para‐cancer tissues." (PMID 36639836, 2023). "ACSL5 expression is down‐regulated in ATII of IPF, ADC, para‐cancer and SSC tissues." (PMID 36639836, 2023). "The predicted estimation of being diagnosed with cancer from the log it model based on the five selected lipogenic genes panel, and Log it (P) = 0.429 + 0.659 x ACOT8 + 0.084 x ACSL5 + 0.029 x FASN + 0.201 x HMGCS2 + 0.119 x SCD1 was used to create the ROC curve." (PMID 32155177, 2020). "At the present time, the precise functions of ACSL5, MLPH and TMEM45B in cancer remain unknown." (PMID 24625834, 2014). "Validation of the whole-body mouse knockout of some isoenzymes such as ACSL3, ACSL5 and ACSL6 does not result in lethality or any overt dysfunction which renders them cancer cell specific vulnerabilities." (PMID 31344914, 2019).